PPARG (peroxisome proliferator activated receptor gamma)
Diseases named in the same sentence as PPARG in open-access papers (continued):
Sharing a sentence is not in itself a finding about the gene and the disease.
bladder cancer (continued). "Overall, despite the limitations of the study, the data presented here fulfill the major aim of our study, and provide a valuable resource for the community that can serve to support future work investigating PPARγ biology in bladder cancer." (PMID 37250326, 2023). "PPARγ is now well defined as a key transcription factor in a major subset of bladder cancer, in which it acts to promote tumor growth through cell intrinsic and extrinsic mechanisms." (PMID 37250326, 2023). "In summary, this work provides a resource and biological insights to aid our understanding of PPARG regulation in bladder cancer." (PMID 37250326, 2023). "Contrarily, it has been reported that the activation of PPARγ/RXRα induces the microenvironmental reprogramming in the bladder cancer, which is beneficial to the tumorigenesis." (PMID 37976136, 2023). "and PPARG signaling has been reported to have an important influence on immune rejection in patients with bladder cancer." (PMID 36911676, 2023). "Both FOXA1 and GATA3 also play a role in the differentiation of urothelial cells in human bladder cancers, and the expression of PPARγ, FOXA1 and GATA3 is negatively correlated to the grade of the tumor." (PMID 36293167, 2022). "Collectively, this study provides evidence that SNHG1 upregulation promoted cell proliferation but depressed cell apoptosis in bladder cancer via MDM2-inhibited PPARγ by binding to miR-9-3p." (PMID 36230661, 2022). "More importantly, it was elaborated in a prior study that an antagonist of PPARγ promoted cell cycle entry and decreased cell apoptosis in bladder cancer." (PMID 36230661, 2022). "This network module has 6 putative bladder cancer drivers including PPARG and CDK9 and the known bladder cancer driver ERBB3." (PMID 35035776, 2022). "Through a PPARγ-mediated pathway, etomoxir induces bladder cancer cell cycle arrest in the G0/G1 phase and alters gene expression related to fatty acid metabolism." (PMID 35743814, 2022). "Rather, lineage plasticity in bladder cancers with squamous differentiation is associated with loss of expression of FOXA1, GATA3, and PPARG, transcription factors critical for maintenance of urothelial cell identity." (PMID 36323682, 2022). "In bladder cancer, fatty acid metabolism is activated, and the PPARγ antagonist GW9662 reverses cell cycle arrest." (PMID 35743814, 2022). "We found that lineage plasticity in bladder cancers with SqD was associated with loss of expression of the FOXA1, GATA3, and PPARG transcription factors." (PMID 36323682, 2022). "Overall, the role of PPARγ signaling in bladder cancer is still controversial and further studies are needed in the future." (PMID 35418978, 2022). "PPARγ has a protumorigenic role in luminal MIBCS, as the loss of PPARγ expression impairs the bladder cancer cell viability." (PMID 33716977, 2021). "For instance, PPARγ agonist rosiglitazone treatment-induced adverse events such as bladder cancer and heart failure have become highly aware in clinical application." (PMID 34745420, 2021). "Simultaneous PPARγ activation improved the anti-tumor activity of ABT510 in bladder carcinoma bearing mice." (PMID 32785018, 2020). "Taken together, this review summarizes the relevant literature and our findings to explore the complicated role and function of PPARγ in bladder cancer." (PMID 32328200, 2020). "In BC cell lines, studies by others have shown that have shown that GATA3 and FOXA1 cooperate with PPARγ activation to drive the differentiation of a basal bladder cancer subtype to a more differentiated luminal subtype." (PMID 32822399, 2020). "Our results and previous studies showed that PPARγ plays a significant role in the occurrence and progression of bladder cancer through regulation of proliferation, apoptosis, metastasis, and reactive oxygen species (ROS) and lipid metabolism 6-10." (PMID 32328200, 2020).
bladder cancer (continued). "There is accumulating evidence for tumorigenic roles of PPARγ in a variety of cancers, including colon, breast, lung, prostate and bladder cancers." (PMID 33266062, 2020). "In bladder cancer, TM4SF1 deficiency significantly upregulated PPARγ and forkhead transcription factor 3a (FOXO3a) and downregulated SIRT1 protein expression, forming a feedback loop that modulates the cell cycle." (PMID 33015133, 2020). "The exact role of PPARγ signaling in carcinogenesis is somewhat unclear, however, the expression of PPARγ in bladder cancers is a favorable prognostic marker." (PMID 32822399, 2020). "Unfortunately, few studies have investigated the synergistic effects of PPARγ agonists and chemotherapy drugs, such as gemcitabine and docetaxel, in bladder cancer." (PMID 32328200, 2020). "Considering the frequent relapses after chemotherapy, some researchers have focused on the relationship between PPARγ and chemotherapy sensitivity in bladder cancer." (PMID 32328200, 2020). "The purpose of this paper is to provide an overview of the role, function and potential molecular mechanisms of PPARγ in bladder cancer." (PMID 32328200, 2020). "Most studies showed that PPARγ activation markedly inhibited cell proliferation, induced cell cycle arrest and promoted apoptosis in bladder cancer cells and suppressed tumor growth or metastasis in vivo 108-112." (PMID 32328200, 2020). "Previous studies have compared bladder cancer with paracancerous tissues, and showed the controversial consequences of the expression of PPARγ in bladder cancer." (PMID 32328200, 2020). "Accumulating evidence implicates PPARG as a key gene in bladder cancer, but the functional effect of PPARG in tumor development are controversial." (PMID 30845932, 2019). "Taken together, these data indicated that PPARγ activation suppresses proliferation of bladder cancer cells by inducing G2 phase cell cycle arrest and apoptosis." (PMID 30845932, 2019). "Our results revealed that PPARγ was up‐regulated in human bladder cancer (BCa) tissues both at transcriptional and translational levels." (PMID 30912275, 2019). "This study demonstrated the tumor-suppressive effect of PPARγ agonists rosiglitazone and pioglitazone in bladder cancer." (PMID 30845932, 2019). "In further, we confirmed the suppressive effect of PPARγ activation on Akt phosphorylation in bladder cancer with the subcutaneous tumor models." (PMID 30845932, 2019). "In this study, we found MIBC patients from our cohort and the TCGA database markedly benefited from higher expression levels of PPARG with longer overall survival, suggesting the favorable action of PPARγ in bladder cancer." (PMID 30845932, 2019). "PPARG was identified as a significant focal amplification specifically in bladder cancer by genome identification of significant targets in cancer (GISTIC) analysis." (PMID 30845932, 2019). "By activating PPARγ, simvastatin inhibited bladder cancer cell proliferation and induced cell cycle arrest at G1/G0 phase." (PMID 30845932, 2019). "In the present study, we focused on the intrinsic changes of bladder cancer cells that induced by the alteration of PPARγ." (PMID 30845932, 2019). "Another in vitro study also showed that reducing PPARγactivity through pharmacologic inhibition or genetic ablation inhibited proliferation of PPARγ-activated bladder cancer cells." (PMID 30845932, 2019). "Here, we report recurrent mutations of PPARγ that also activate the PPARγ/RXRα pathway, conferring PPARγ-dependency and supporting a crucial role of PPARγ in luminal bladder cancer." (PMID 30651555, 2019). "The functional effects of PPARγ on cell proliferation, cell cycle and apoptosis were determined in human bladder cancer cells with pharmacological activation and inhibition of PPARγ." (PMID 30845932, 2019).
bladder cancer (continued). "Accumulating evidence implicates PPARG as a key gene in bladder cancer development; however, observations regarding the functional effect of PPARG alteration on the development of bladder cancer are controversial." (PMID 30845932, 2019). "Next we determined the effect of PPARγ activation or inhibition on the cell cycle progression of bladder cancer cells." (PMID 30845932, 2019). "In the tissue array of a retrospective cohort of 66 patients with bladder cancer, the protein level of PPARγ expression was evaluated by immunohistochemistry staining." (PMID 30845932, 2019). "The PPARγ agonist troglitazone induces autophagy, apoptosis and necroptosis in bladder cancer cells." (PMID 30845932, 2019). "PPARγ activation by rosiglitazone and pioglitazone markedly induced cell cycle G2 arrest and apoptosis in bladder cancer cells, which resulted in inhibition of cell proliferation in vitro and suppression of tumor growth in vivo." (PMID 30845932, 2019). "Together, these data suggests that PPARγ activation inhibits PI3K-Akt signaling pathway in bladder cancer cells." (PMID 30845932, 2019). "Higher expression of PPARγ or its activation by agonists promotes bladder cancer cell migration and invasion." (PMID 30845932, 2019). "Further experiments confirmed that pharmacological activation of PPARγ notably induced cell cycle arrest and apoptosis of bladder cancer cells, which was tightly related to the inhibition of signaling transduction in PI3K-Akt pathway." (PMID 30845932, 2019). "We further validated in bladder cancer Umuc-3 and 5637 cells that phosphorylation of Bcl2, Bad, and FoxO1 was consistently repressed by PPARγ agonist rosiglitazone, but enhanced by the inverse agonist T0070907." (PMID 30845932, 2019). "Our study provides additional genetic evidence for a pro-tumorigenic role of PPARγ in bladder cancer and strengthens the importance of the PPARγ/RXRα pathway in luminal bladder cancer." (PMID 30651555, 2019). "Our data suggested that PPARγ activation suppressed bladder cancer through inhibiting PI3K-Akt signaling pathway." (PMID 30845932, 2019). "To determine the functional effect of PPARγ in bladder cancer, we next tested the effect of pharmacologic activation and inhibition of PPARγ on the cell growth in Umuc-3 and 5637 cells." (PMID 30845932, 2019). "Collectively, these data reinforce the anti-inflammatory role of tumor-intrinsic PPARγ/RXRα activity and potentially as a driver of resistance to immune checkpoint inhibitor therapies in bladder cancer." (PMID 28740126, 2017). "Global transcriptome profiling revealed a significant overlap of differentially expressed genes between the PPARγ, RXRαS427F and RXRαS427Y overexpressing human bladder cancer lines relative to their respective controls." (PMID 28740126, 2017). "Here, we report that hotspot S427F/Y mutations in RXRA or focal amplification/overexpression of PPARG in bladder cancer induce the activation of the PPARγ/RXRα pathway, leading to suppression of cytokine secretion from cancer cells." (PMID 28740126, 2017). "We demonstrate that recurrent alterations in PPARγ/RXRα heterodimer lead to enhanced PPARγ signaling, reinforcing the importance of this pathway in bladder cancer biology." (PMID 28740126, 2017). "More notably, high levels of PPARγ are selectively expressed in the transitional epithelium of the ureter and urinary bladder, the area where bladder cancer typically arises." (PMID 28348577, 2017). "A role for PPAR activity in promoting bladder cancer is supported by the presence of a PPARG gene amplification in 17% of cases." (PMID 29143738, 2017). "The 5637 bladder cell line had a considerably higher mRNA and protein expression of PPARγ compared to other bladder cancer cell lines such as UMUC-3." (PMID 28348577, 2017). "Copy number analysis identified PPARG as amplified in 17% of bladder cancer cases, with PPARG amplified cases being highly enriched for PPARG mRNA expression (q value = 2.6 × 10-9)." (PMID 29143738, 2017).
bladder cancer (continued). "Located at the center of the focal amplicon in chromosome 3p, PPARG was identified as a significant focal amplification specifically in bladder cancer by genome identification of significant targets in cancer (GISTIC) analysis." (PMID 28740126, 2017). "We found that knockdown of PPARγ significantly augmented chemokine-related immune pathway activity in bladder cancer cells." (PMID 28740126, 2017). "Taken together, our study for the first time revealed that simvastatin inhibited bladder cancer cell proliferation and induced cell cycle arrest at G1/G0 phase via PPARγ signalling pathway." (PMID 27779188, 2016). "Since our transcriptome analysis suggested the link between lipid/fatty acid metabolism and PPAR signalling pathway in bladder cancer, and we noted an induction of PPARγ at protein and functional level in the simvastatin-treated BCa cells." (PMID 27779188, 2016). "As evaluated by MTT assays, gefitinib (EGFR inhibitor) and DIM-C (PPARγ agonist) inhibited growth of 9 bladder cancer cell lines in a dose-dependent manner but with variable sensitivity." (PMID 23409107, 2013). "This is, to our knowledge, the first report that suggests a possible explanation for the elevated expression of PPARG in bladder cancer confirming its critical role in initiation and maintenance of this type of tumor." (PMID 23114535, 2012). "A possible role for PPARG in bladder cancer has been suggested since it was expressed at higher levels in tumor specimens than in benign urothelium." (PMID 23114535, 2012). "Taken together, this set of experiments established that in T24 bladder cancer cells, ciglitazone induced apoptosis through PPARγ activation-independent signalling pathways." (PMID 22174792, 2011). "According to our study, it is needed to elucidate in bladder cancer the distinct PPARγ-independent mechanisms of ciglitazone action prior to clinical exploration." (PMID 22174792, 2011). "In further support of a PPARγ-independent mechanism, the TZD ligands and 15dPGJ2 produced comparable growth inhibition in the TSU-Pr1/TSU-Pr1-B1/TSU-Pr1-B2 bladder carcinoma series despite increasing PPARγ expression." (PMID 16519808, 2006). "In this study we have utilized a broad range of PPARγ agonists and the PPARγ-selective antagonist GW9662, to examine the effect of PPARγ activation in prostate and bladder carcinoma cell lines." (PMID 16519808, 2006). "Our findings demonstrate that the effects induced by TGZ and 15dPGJ2 in prostate and bladder carcinoma are PPARγ-independent." (PMID 16519808, 2006). "Troglitazone and 15dPGJ2 inhibit growth of prostate and bladder carcinoma cell lines through different mechanisms and the effects of both agents are PPARγ-independent." (PMID 16519808, 2006). "Although the interaction of PPARG with AR in bladder cancer remains uninvestigated, evidence suggests that PPARG affected bladder cancer development and progression by regulating metastasis, apoptosis, proliferation and reactive oxygen species (ROS) and lipid metabolism." (PMID 40458476, 2025). "In BASQ bladder cancers, PPARG expression is significantly downregulated." (PMID 41438986, 2025). "Moreover, PPARG expression in human MIBC tissues inversely correlated with CD8 infiltration, further confirming an association of PPAR-γ with immune evasion in bladder cancer." (PMID 41148824, 2025). "Furthermore, the treatment of a PPARγ inhibitor reversed the effects of bergenin on the activity of bladder cancer cells, namely, in terms of proliferation, apoptosis, invasion, and migration." (PMID 39834829, 2024). "Future studies that combine whole-genome activator and knockout screens in both luminal and basal bladder cancer will provide a comprehensive framework of the various positive and negative regulatory mechanisms that are necessary and/or sufficient to modulate PPARG gene expression in MIBC." (PMID 37250326, 2023).
bladder cancer (continued). "In addition, we reported that the histone chaperone SPT6 is important in sustaining PPARG expression bladder cancer cells." (PMID 37250326, 2023). "This controversial effect could be because of PPARγ may be involved in both the tumor-suppressive and oncogenic roles of PPARγ in bladder cancer." (PMID 36834611, 2023). "The study proposes that the transactivation of PPARγ could be served as a potential strategy for the chemoprevention and therapeutic treatment of bladder cancer." (PMID 36834611, 2023). "Furthermore, we also observed that SV incubation upregulated the mRNA and protein levels of PPARγ in prostate cells, which was parallel to studies on liver cancer cells and bladder cancer cells." (PMID 36902342, 2023). "Therefore, further analysis and validation of the hits identified in our screen has the potential to generate significantly more biological insight into regulators of PPARG expression specifically in bladder cancer cells." (PMID 37250326, 2023). "The expression of PPARG was augmented in patients with early stage bladder cancer." (PMID 37197716, 2023). "Additionally, evidence from in vivo studies showed the PPARG dependency of bladder urothelial carcinoma and PPARG promotes bladder cancer progression through Sonic Hedgehog signaling-related cellular autonomic mechanisms." (PMID 37197716, 2023). "Finally, these data support the utility of the reporter system to assess potential therapies targeting pathways that regulate PPARG gene expression in luminal bladder cancer." (PMID 37250326, 2023). "Recently, it has been suggested that PPARγ may be a favorable prognostic factor in patients with bladder cancer." (PMID 36834611, 2023). "In bladder cancer, the potential of PPARG as a biomarker has been confirmed." (PMID 38044948, 2023). "We identified and validated GATA3 as a positive regulator of PPARG in bladder cancer." (PMID 37250326, 2023). "So, it remains unclear what specific role PPARγ signaling plays in the development and prognosis of bladder cancer." (PMID 35418978, 2022). "The reduction of the activity of PPARG, whether through drug inhibition or gene ablation, would inhibit the proliferation of bladder cancer cells." (PMID 35656081, 2022). "Taken these findings into account, we hypothesized that the SNHG1/miR-9-3p/MDM2/PPARγ axis correlated to the progression of bladder cancer." (PMID 36230661, 2022). "Furthermore, MDM2 induced ubiquitination and degradation of PPARγ that contributed to the development of bladder cancer." (PMID 36230661, 2022). "Studies have revealed that PPARG exerts a vital role in a number of tumors, including colorectal (Villa, Parra, Feitosa, Camargo, Machado, Tirapelli, Rocha and Feres 2020), renal, and bladder cancers." (PMID 36712863, 2022). "In 12–17% of the muscle-invasive bladder carcinomas (MIBC) and in 10% of the non-muscle-invasive bladder carcinomas, PPARγ focal amplifications leading to PPARγ overexpression have been reported, suggesting a role for PPARγ in the initiation and maintenance of bladder cancer." (PMID 33716977, 2021). "On the one hand, PPARγ expression has been associated with good prognosis in CRC67 and the use of the PPARγ agonists troglitazone and rosiglitazone inhibited tumorigenesis in CRC and bladder cancer models by a tumor-directed effect." (PMID 33953160, 2021). "PPARg is differentially expressed in bladder cancer subtypes." (PMID 34697317, 2021). "The decrease in the expression of KRT14 in the UROtsa parent and transformed cells suggests that the activation of PPARγ or inhibition of cell proliferation may decrease the regenerative capacity of the normal urothelium as well as bladder cancers." (PMID 32822399, 2020). "Therefore, more bladder cancer tissue samples from different races, ages, tumor stages and grades need to be analyzed to investigate the clinical relevance of the expression of PPARγ in bladder cancer." (PMID 32328200, 2020).